PLVAP (plasmalemma vesicle associated protein)
Diseases named in the same sentence as PLVAP in open-access papers (continued):
Sharing a sentence is not in itself a finding about the gene and the disease.
tumor (continued). "Thus, it is suggested that the regulation of PLVAP expression on ECs may be related to the secretion of TGFβ1 by tumour cells." (PMID 41431249, 2025). "This study identifies endothelial PLVAP as a prognostic marker in LUAD, linking tumour‐derived TGFβ1 to PLVAP‐driven vascular remodelling and tumour invasiveness." (PMID 41431249, 2025). "In conclusion, our results suggest a nexus between malignant/HPC-like cells, onco-fetal PLVAP+ ECs, and FOLR2+ TAMs in the immunosuppressive tumor ecosystem." (PMID 36238304, 2022). "In a spatial context, we also observed high expression of PLVAP and CA2 within the tumor infiltrated region." (PMID 36180422, 2022). "Endothelial cells from different sources were mixed and assigned to four cell types, including immune EDCs (CCL5 and CXCL13), lymphatic EDCs (PDPN and PROX1), tumor EDCs (ACKR1 and POSTN), and vascular EDCs (PLVAP and SLC9A3R2)." (PMID 34697289, 2021). "Evidence has demonstrated that PLVAP expression is regulated by VEGF signaling and interacts with tumor angiogenesis." (PMID 22606345, 2012). "Although bulk RNA‐seq datasets mainly reflect whole tumour tissues, PLVAP is specifically expressed in TECs and not in EPs." (PMID 41431249, 2025). "Furthermore, we observed increased expression levels of VEGFA and PLVAP with disease progression, suggesting that continuous hypoxia induces increased secretion of VEGFA by tumour cells and activates the VEGFA‐PLVAP axis to promote angiogenesis." (PMID 37994257, 2024). "In addition, PLVAP + endothelial cells (Endo-PLVAP) were enriched in the tumor boundary and exhibited interactions with Macro-SPP1, Fib-APSN, and tumor cells." (PMID 36806082, 2023). "Consistent with this phenomenon, we found that VEGFA was highly expressed in malignant/HPC-like cells, while PLVAP+ ECs notably expressed its receptor KDR (VEGFR2), suggesting that these cells may interact within the tumor microenvironment." (PMID 36238304, 2022). "Notably, CEP192 was highly correlated with multiple tumor-associated cytokine ligand–receptor axes, including IL11–IL11RA, IL6–IL6R, and IL13–IL13RA1, which could promote interactions between hepatic progenitor-like cells, PLVAP+ endothelial cells, tumor-associated macrophages, and CD4+ T cells." (PMID 36238304, 2022). "This is the first report showing PLVAP expression in AGCT cells, but the function of this gene in the tumor cells remains unknown." (PMID 35723333, 2022). "First, we categorized clustered data into tumor and stromal populations using a panel of markers for each (epithelial: AQP1, AQP2, EPCAM; endothelial: PLVAP, CD31, CD34; fibroblast: PDGFRα, PDGFRβ; immune: CD45; tumor cell: CXCR4, VIM, KRT18, PAX8, PAX2, CA9, CD10)." (PMID 34884982, 2021). "Endothelial cells that highly expressed ACKR1 and PLVAP could enhance the transmigration of lymphocytes, and GRN was found to promote angiogenesis and tumor cell proliferation." (PMID 34805166, 2021). "In contrast to upregulation of PLVAP in Co1 ECs, the expression of tight-junction molecules, including CLDN5, was similar between ECs in the periphery and tumor core, highlighting an important role of transcellular pathways for BBB breakdown and the edema formation observed in GBM." (PMID 34228647, 2021). "PLVAP expression did not correlate with the growth pattern of the tumor, tumor size, or relapse." (PMID 35723333, 2022). "The sub‐clustering of ECs revealed six subtypes, including extra‐alveolar capillary EC (cEC) (FCN3+EDN1+PLVAP+), alveolar cEC (HPGD+EDNRB+IL1RL1+), arterial EC(GJA5+FBLN5+DKK2), lymphatic EC (CCL21+TFF3+FABP4), INSR+ tumour EC (INSRhiHSPG2+PLVAP+), and ACKR1+ tumour EC (ACKR1+SELP+IL1R1+)." (PMID 35184398, 2022). "Through a comparative study of gene expression in paired tumor and adjacent non-tumorous tissues, we discovered that PLVAP protein was specifically expressed in vascular endothelial cells of HCC and not in vascular endothelial cells of non-tumorous liver tissue." (PMID 25376302, 2014).
tumor (continued). "PLVAP expression was also higher in the endothelial cells of stage Ib-III primary tumors compared with endothelial cells of stage Ia primary tumors (p < 0.05, n = 105), but not in the tumor cells." (PMID 35723333, 2022).
cancer (15 papers, 2018 to 2025). A tumor composed of atypical neoplastic, often pleomorphic cells that invade other tissues. "Our study suggests that directly targeting liver endothelium, specifically PLVAP, could selectively shape the senescence-driven immune microenvironment and have a critical impact on tissue regeneration/cancer risk that accompanies chronic liver inflammation." (PMID 37810232, 2023). "We labeled cell types as endothelial cell (Endothelial, gene expression of PLVAP, KDR, PTPRB) and cancer associated fibroblasts cell (CAFs, gene expression of FAP, MMP11, PDGFRB, SFRP2, PDGFRA, ADAMTS2)." (PMID 37065499, 2023). "CLEC4G which is an underexpressed gene in cancer is the chief performer with AUC ~0.99 at threshold 2.9; whereas PLVAP is overexpressed gene in cancer samples, it can distinguish samples with AUC 0.97 at threshold 3.8." (PMID 31490960, 2019). "In addition, the PLVAP gene, which is involved in the structure of the diaphragm and vascular fenestrations identified in the cancer group, may be a downstream target of VEGF signaling, and is also an important factor in angiogenesis." (PMID 31747953, 2019). "We also identified a novel gene associated with the risk of BRONJ that is involved in angiogenesis in patients of cancer BRONJ, PLVAP, which is the VEGFA downstream signaling target involved in the structure of the diaphragm and functions in vascular fenestrations." (PMID 31747953, 2019). "In the cancer group, ARIDS, HEBP1, LTBP1, and PLVAP were identified as candidate genes." (PMID 31747953, 2019). "Similarly, fibroblast-like cancer cells (C10) and endothelial cell-like cancer cells (C11) were identified based on the specific expression of fibroblast markers (DCN, COL1A2 and COL6A3) and endothelial cell markers (PCAT19, VWF and PLVAP)." (PMID 36451812, 2022).
infection (11 papers, 2013 to 2025). The state of being infected such as from the introduction of a foreign agent such as serum, vaccine, antigenic substance or organism. "No amplification of GKN3 was observed while there was significant up-regulation of PLVAP at 30 min post infection." (PMID 30082709, 2018). "At these early time points of infection, PLVAP was shown to be localized at the neuronal membrane." (PMID 30082709, 2018). "mRNA expression profiles of PLVAP and GKN3 were validated by qRT-PCR and higher expression was found at 15 and 30 min post infection." (PMID 30082709, 2018). "At both early time points post infection, JEV was found to be co-localized with PLVAP and GKN3." (PMID 30082709, 2018).
central nervous system disease (1 paper, 2018). "Here, we discuss the current understanding of PLVAP as a structural component of endothelial cells and regulator of vascular permeability in health and central nervous system disease." (PMID 30231925, 2018).
ischaemic heart disease (1 paper, 2024). "Additionally, this study identified plasmalemma vesicle-associated protein (Plvap) as a novel endothelial-specific marker of cardiac neovasculogenesis, which was also identified in cardiac samples from patients with ischaemic heart disease." (PMID 39519298, 2024).
PLVAP also shares sentences with these, for which no sentence is quoted: HCMV infection (3 papers); poliomyelitis (3); ischemia (2); ischemic stroke (2); pancreatic cancer (2); abetalipoproteinemia (1); adenocarcinoma (1); alcoholic liver diseases (1); anemia (1); Ascites (1); astrocytomas (1); autoimmune disorders (1); autoimmune uveitis (1); bacterial sepsis (1); bladder cancer (1); brain arteriovenous malformations (1); breast carcinoma (1); Cerebral ischemia (1); cerebral malaria (1); clear cell renal cell carcinoma (1); cognitive disorder (1); COVID-19 (1); Cyanosis (1); diabetic kidney disease (1); diabetic macular edema (1); dyskeratosis congenita (1); enteropathy (1); experimental autoimmune encephalomyelitis (1); gastric tumors (1); glomerulonephritis (1).
A further 28 diseases each share a sentence with PLVAP in 1 paper.